RN7SL138P (RNA, 7SL, cytoplasmic 138, pseudogene)
Gene: Miscellaneous RNA gene on chromosome 17 (30,959,564 to 30,959,850, forward strand). Ensembl gene ENSG00000266274.
Homologues: Orthologues: chimpanzee Metazoa_SRP (98% identical), macaque Metazoa_SRP (76% identical). Paralogues in human: RN7SL2 (82% identical), RN7SL1 (81% identical), RN7SL3 (79% identical), RN7SL828P (79% identical), RN7SL218P (79% identical), RN7SL769P (79% identical), RN7SL239P (78% identical), RN7SL712P (78% identical), RN7SL444P (78% identical), RN7SL714P (78% identical), RN7SL113P (78% identical), RN7SL44P (78% identical), and 700 more.